INS (insulin)
Diseases named in the same sentence as INS in open-access papers (continued):
Sharing a sentence is not in itself a finding about the gene and the disease.
metabolic syndrome (continued). "Improved insulin sensitivity, lipid profile, and redistribution of body fat induced by berberine offer a promising future prospect to prevent cardiovascular disease and metabolic syndrome in patients with PCOS." (PMID 35251851, 2022). "Current studies on the relationship between diet and metabolic syndrome focus on the efficacy of regulation of intestinal microflora in terms of weight maintenance and insulin sensitivity recovery, as well as calorie restriction and macronutrient supplementation." (PMID 36145077, 2022). "However, surprisingly, they clearly correlate with the values of blood pressure, insulin, FI and WI measured at the end of the experiment, all of them being metabolic syndrome markers, as well as negatively with body weight at this timepoint." (PMID 35972974, 2022). "Furthermore, chronic administration of FGF21 analogs ameliorates dyslipidemia and reduces body weight in obese and T2D patients, and also decreases fasting insulin levels while increasing adiponectin levels." (PMID 35563026, 2022). "Clinical trials have shown that the Mediterranean diet, in addition to reducing liver fat, improves insulin sensitivity and helps the reversion of metabolic syndrome, even without weight loss." (PMID 36145146, 2022). "Dietary n-3 PUFAs, especially long-chain n-3 PUFAs, including docosahexaenoic acid (DHA) and eicosapentaenoic acid (EPA), have anti-inflammatory and antioxidant properties, which improve insulin resistance and lipid metabolism and ameliorate obesity and dyslipidemia." (PMID 36005486, 2022). "Indeed, pilot studies have reported that transplantation from lean donors to patients with metabolic syndrome improved insulin sensitivity." (PMID 35208906, 2022). "An insulin pathway is a key event linking metabolic syndrome with cancer." (PMID 36497428, 2022). "It remains not fully understood how ADT may directly cause serious cardiovascular events, but there is evidence that ADT has a detrimental metabolic impact, can decrease insulin sensitivity and lead to dyslipidemia." (PMID 35489025, 2022). "Although IL-6 levels were associated with waist circumference, BMI, HbA1c, and insulin levels the association with metabolic syndrome was not statistically significant." (PMID 35135482, 2022). "Moreover, in addition to normalization of the insulin level, among rodents with metabolic syndrome, the effect on leptin and adiponectin levels reverses their abnormalities." (PMID 35406122, 2022). "Normal gestational metabolism, regulated by multiply hormones, was accompanied by a physiological increase in glucose, insulin resistance and insulin levels, as well as serum lipids such as triglycerides and free fatty acids, which resembled a “metabolic syndrome” as outlined beyond pregnancy." (PMID 36014853, 2022). "ECs with metabolic syndrome used more fat in relation to insulin‐stimulated NOGD." (PMID 36123314, 2022). "Recent studies have indicated that TRF improves insulin sensitivity and reduces body weight, blood pressure, atherogenic lipids and oxidative stress in patients with metabolic syndrome, while prevents obesity and metabolic syndrome in mice lacking a circadian clock." (PMID 36618695, 2022). "Bempedoic acid may decrease gluconeogenesis leading to improved insulin sensitivity, glucose metabolism, and metabolic syndrome." (PMID 36386319, 2022). "However, the interaction between metabolic syndrome and the gender dimorphism of brain insulin sensitivity remains to be determined." (PMID 35111373, 2022). "Previous mechanistic studies have shown that the improvement of dyslipidemia induced by a ketogenic diet may not only benefit the regulation of insulin sensitivity, but also control and prevent the occurrence and progression of related complications." (PMID 36012064, 2022). "They suggested that flavonoids could improve insulin sensitivity, dyslipidemia, inflammation, and pancreatic β cell viability." (PMID 35937400, 2022).
metabolic syndrome (continued). "Therefore, improved dyslipidemia is not only beneficial for regulating insulin sensitivity, but also protects against cardiovascular disease." (PMID 36583214, 2022). "It is known that hypomagnesemia may contribute to lower insulin secretion, which may affect lipid metabolism leading to dyslipidemia." (PMID 35165581, 2022). "These bioactive compounds may help to regulate body weight, improve metabolic syndrome and thereby improve insulin sensitivity and reduce resistance." (PMID 36704786, 2022). "Based on this concept, our results suggest that regular mixed exercise (jogging and weight training) may improve HDL-C levels, which could in turn increase reverse cholesterol transport and insulin sensitivity, reducing CVD and metabolic syndrome risk." (PMID 36518491, 2022). "However, in vivo treatment with the AhR agonist Ficz alleviates the metabolic impairments (e.g., insulin and glucose dysmetabolism, intrahepatic lipid accumulation, and dyslipidemia) in both diet- and genetic-induced metabolic syndrome." (PMID 36144238, 2022). "Insulin sensitivity plays an important role in the development of NAFLD in metabolic syndrome." (PMID 35723298, 2022). "The insulin/IGF-1/AKT pathway is a key event linking metabolic syndrome with endometrial cancer." (PMID 36497428, 2022). "In addition, it has been reported that these FAs have a correlation to parameters that are related to glucose metabolism such as insulin and HbA1c in metabolic syndrome." (PMID 36013484, 2022). "Indeed, studies have described the health-promoting effects of Akkermansia on energy metabolism and metabolic functions such as insulin sensitivity, dyslipidemia, and even cognition." (PMID 36235574, 2022). "Of note, semi-partial r values revealed that IGFBP-1 accounts for a greater fraction of the variance than body fatness for all indices of insulin sensitivity but not for indices of dyslipidemia risk, except for HDL cholesterol." (PMID 35586622, 2022). "The gut-centric theory of metabolic syndrome posits that an unhealthy diet (for example a diet rich in fat and poor in fibers) permits the growth of pathogens in the colon, leading to metabolic endotoxemia and impaired insulin sensitivity." (PMID 36551210, 2022). "Future studies of insulin-sensitizing medications should measure metabolic markers, and ideally use a standard panel of such markers, may be one including all features of metabolic syndrome." (PMID 36347837, 2022). "Thin donor FMT improves insulin sensitivity in obese people with metabolic syndromes." (PMID 36542005, 2022). "However, they reported that in utero exposure to increased blood insulin levels resulted in increased offspring BMI and the onset of metabolic syndrome." (PMID 36557264, 2022). "Similarly, VAT ZAG groups showed differences in waist circumference and weight, and some additional characteristics concerning the metabolic syndrome, such as insulin and HOMA-IR." (PMID 35884810, 2022). "Similarly, grape seed extract improved insulin concentration and insulin sensitivity in adolescents with metabolic syndrome." (PMID 35624760, 2022). "Other than FPG and insulin, the symptoms of IR may manifest as dyslipidemia due to its influence on the liver." (PMID 36159483, 2022). "In this review, we mainly focus on the relationship between metabolic syndrome and neurodegenerative diseases, exploring the role of hypercaloric diets in brain function and the physiological role of insulin and insulin resistance in the central nervous system (CNS)." (PMID 35406040, 2022). "Subjects with 3 and more risk factors of MetS showed a 69% reduction in myocardial insulin-stimulated glucose metabolism than subjects with no risk factors, and a 56.7% reduction than those with 1 or 2 components of the metabolic syndrome." (PMID 35845046, 2022).
metabolic syndrome (continued). "We previously reported the effect of 4-week dawn-to-dusk dry fasting on the same subjects’ metabolic syndrome components (e.g., weight, waist circumference, blood pressure, glucose), insulin, lipid panel, hepatic panel, and adiposity, oxidative stress, and inflammation biomarker levels." (PMID 36506940, 2022). "The study suggests that VDS could improve insulin concentration and dyslipidemia in the elderly population." (PMID 35752843, 2022). "From another perspective, the overlap implies that brain aging itself may be a metabolic syndrome driven by impaired brain insulin signaling and glucose metabolism, the same processes that, outside the brain, are well-established with respect to T2DM." (PMID 35608247, 2022). "Indeed, on metabolic syndrome and comorbidities, lycopene was reported to improve carbohydrate and lipid homeostasis through increased insulin-sensitivity, adiponectine levels and dyslipidemia modulation (increased High-Density Lipoprotein, HDL)." (PMID 35684524, 2022). "We did not account for the impact of these indicators (blood glucose, insulin levels, adiponectin, leptins) on dyslipidemia and may underestimate the prevalence of dyslipidemia." (PMID 35684121, 2022). "Dyslipidemia may be due to increased lipolysis from a highly inflammatory background, which would be aggravated in T2D where fatty tissues lose sensitivity to insulin’s anti-lipolytic effects." (PMID 35957811, 2022). "In addition to these elevated metabolic and circulatory markers, like dyslipidemia and elevated insulin levels." (PMID 36518462, 2022). "Carotid IMT is reported to be significantly higher among women with PCOS compared with controls, and may be related to higher insulin levels, dyslipidemia, and abdominal obesity reported in women with PCOS." (PMID 35329952, 2022). "Body weight and fat mass were lower in Mas-ko compared to wt mice, which is on the one hand the opposite of other findings of the same group showing higher body weight and fat mass, as well as dyslipidemia and higher levels of insulin and leptin in Mas-ko mice." (PMID 35431918, 2022). "A low-carbohydrate diet combined with conventional medication may improve the clinical course of acne disease and insulin sensitivity in young men who are resistant to dermatological drug therapy and have high levels of IR and metabolic syndrome features." (PMID 36678524, 2022). "However, other short-term studies have shown a lack of effect of etanercept on markers of insulin secretion and insulin sensitivity in patients with CIRDs and T2D or metabolic syndrome." (PMID 35629988, 2022). "Metabolic syndrome is described as a pre-diabetic condition that includes obesity, dyslipidemia, impaired fasting glucose and/or impaired glucose tolerance, and reduced insulin sensitivity." (PMID 35889791, 2022). "Hormone replacement therapy (HRT), provided the selected progestin does not antagonize estrogen action, may improve fat mass and distribution, dyslipidemia, and insulin sensitivity in postmenopausal women." (PMID 36295856, 2022). "Dyslipidemia during pregnancy, especially hypertriglyceridemia, was closely associated with a greater risk of GDM, and the possible mechanisms including impaired insulin action, β-cell function, and nitric oxide signaling." (PMID 35858832, 2022). "The increased prevalence of MetS among women could be attributable to hormonal oral contraceptive uses that can decrease the sensitivity of muscles to insulin which in turn can lead to impaired glucose metabolism and dyslipidemia." (PMID 35104300, 2022). "We previously reported that dawn-to-dusk (sunset) dry fasting was associated with anti-cancer serum proteome response and upregulated several key regulatory proteins of tumor suppression, DNA repair, insulin signaling, and immune regulation in healthy subjects and subjects with metabolic syndrome." (PMID 36506940, 2022).
metabolic syndrome (continued). "The ANS also controls insulin target tissues such as liver, muscle (mostly under sympathetic control), and adipose tissues, and unbalanced ANS plays a causal role in the setting of metabolic syndrome." (PMID 35681432, 2022). "While TNF‐α appears to be more involved in the mechanism and progression of the metabolic syndrome (e.g., reduced insulin sensitivity through an increase in JNK1/2 activation), IL‐6 is likely only a marker of metabolic syndrome since it has been shown to increase lipolysis and fat oxidation." (PMID 35312183, 2022). "Analyzing the correlations between the fat mass and the parameters related to the metabolic syndromes, including the insulin sensitivity and glycemia of WHS, could support this assumption." (PMID 35011083, 2022). "Significant associations were also observed between GDF15 and components of metabolic syndrome, specifically, levels of serum triglycerides (beta = 0.13, p-value = 2.4 × 10–22), fasting insulin (beta = 0.10, p-value = 1.2 × 10–13) and waist-to-hip ratio (WHR) (beta = 0.049, p-value = 7.0 × 10–10)." (PMID 35916366, 2022). "In vivo studies in mice have shown the Rho GEFs P-Rex2, Vav2, Vav3 and PDZ-RhoGEF to be involved in glucose tolerance and/or insulin sensitivity, with deletion of these GEFs either contributing to the development of metabolic syndrome or protecting mice from this disease." (PMID 33923452, 2021). "MCA, that contains high amount of carotenoids, may ameliorate metabolic syndrome and improve insulin sensitivity, and provide an alternative dietary strategy to overcome metabolic syndrome." (PMID 33808007, 2021). "During metabolic syndrome, resistance to insulin which is at the center of its pathophysiology could originate from the oxidative stress generated by hyperuricemia due to disorder cause by obesity." (PMID 35018210, 2021). "Studies have found that Atractylodes lancea volatile oil can effectively reduce the levels of TG, TC, fasting insulin (FINS), fasting blood glucose (FBG), and LDL-C in the serum of rats with metabolic syndrome and improve their insulin sensitivity and HDL-C content." (PMID 34746316, 2021). "The aims of the present study were to quantify plasma resistin concentrations and their relationship with related parameters in healthy horses, in horses with metabolic syndrome/insulin dysregulation, and in horses with acute inflammation, in order to evaluate the usefulness of resistin." (PMID 35011183, 2021). "The role of nuts in the improvement of metabolic health, weight management, and glucose/insulin homeostasis markers and prevention of insulin resistance, hyperinsulinemia, dyslipidemia, and hypertension, the main characteristics of MetS, was suggested but studies are quite rare." (PMID 33976753, 2021). "In addition to the reduced glucose tolerance and insulin sensitivity, HF_HF mice also showed hypercholesterolemia, as reported in many other studies on metabolic syndrome." (PMID 34736458, 2021). "In conclusion, enhancing insulin sensitivity may be a critical mechanism for KD to prevent metabolic syndrome." (PMID 34122092, 2021). "The main problem with the formulation of a paediatric definition of metabolic syndrome is that insulin sensitivity, serum lipid concentrations, and anthropometrical variables change with age, and at least 40 different definitions of metabolic syndrome in children have been used." (PMID 32388582, 2021). "Similarly, the pathogenesis of metabolic syndrome has been theorized to be multifactorial, with lipid and glucose homeostasis issues affecting insulin-sensitive tissues such as the liver, muscles, and adipocytes." (PMID 33920751, 2021). "Nevertheless, it is clear that high saturated fat intake has been associated with increased risk of glucose tolerance impairment, whereas diets with a high proportion of oleic acid can reduce liver steatosis and increase insulin sensitivity in experimental models of metabolic syndrome." (PMID 34440853, 2021).
metabolic syndrome (continued). "Resistance to insulin in skeletal muscle is often followed by systemic hyperinsulinemia, dyslipidemia, hypertension and cardiovascular abnormalities comprising the main indicators of metabolic syndrome." (PMID 34281257, 2021). "Some evidence suggests there may be a beneficial reduction in hemoglobin A1c, daily insulin dose, and body weight mostly in adults, though this may be at the expense of insufficient insulin, dyslipidemia or increased hypoglycemic events." (PMID 33828529, 2021). "Using untargeted metabolomics profiling of fasting plasma, our study aimed at identifying metabolic signatures associated with beneficial properties of alive and pasteurized A. muciniphila when administrated to a cohort of insulin-resistant individuals with metabolic syndrome." (PMID 34812127, 2021). "Univariate logistic regression analysis showed that age, BMI, WC, HC, SBP, DBP, duration of infertility, glucose, insulin, and HOMA-IR were significantly associated with higher chance of dyslipidemia, while LH, FSH, and SHBG were significantly associated with lower chance of dyslipidemia." (PMID 34977197, 2021). "Serum insulin concentration is a significant factor driving metabolic syndrome." (PMID 33917297, 2021). "In addition, it also regulates plasma endotoxin concentration and insulin sensitivity to prevent the occurrence of metabolic syndrome." (PMID 34603565, 2021). "Administered as a subcutaneous weekly injection, it is a manifold single pharmacological agent that has the ability to significantly lower glucose levels, as well as improve insulin sensitivity, reduce weight and amend dyslipidemia favorably modifying the lipid profile." (PMID 34819089, 2021). "For instance, SRT1720 has been demonstrated to extend lifespan and improve metabolic syndrome, insulin sensitivity, and endothelial dysfunction in mice, while a related compound, SRT2104, has undergone clinical phase I and II trials, revealing only minor adverse effects." (PMID 34660673, 2021). "Similarly, rosiglitazone, an insulin sensitizer, ameliorated macrovascular reactivity and ACh-mediated vasodilation in patients with metabolic syndrome." (PMID 34440804, 2021). "In addition, it was suggested that undesirable environmental factors often impair the circadian rhythm, such as circadian release of AVP, leading to the progression of metabolic syndrome with dysregulation of insulin secretion." (PMID 34960038, 2021). "Bacteroides acidifaciens is positively associated with increased insulin sensitivity in peripheral tissues, while the lack of Akkermansia is directly associated with the risk of metabolic syndrome." (PMID 34886561, 2021). "Also, consumption of pomegranate concentrate (50 g for 8 weeks) in obese females with metabolic syndrome led to reduction of glucose, insulin, and insulin resistance and improved markers of metabolic syndrome and cardiac and respiratory endurance." (PMID 34796029, 2021). "FMT was found to have notable effects on the gut microbiome but also on the host plasma metabolome and the epigenome of immune cells providing new avenues of inquiry in the context of metabolic syndrome treatment for the manipulation of host physiology to achieve improved insulin sensitivity." (PMID 34747338, 2021). "Insulin resistance (IR), a pathophysiological state characterized by the attenuated insulin sensitivity of peripheral tissues, is the key feature of metabolic syndrome and type 2 diabetes; and it contributes significantly to the development of atherosclerotic cardiovascular disease." (PMID 34167539, 2021). "Mechanism of action of insulin on amelioration of dyslipidemia is well established." (PMID 33449943, 2021). "Therefore, in this study, we established a rat model of metabolic syndrome and insulin-resistant LO2 cells to explore the role of autophagy in the treatment of metabolic syndrome by KD." (PMID 34122092, 2021).